SPARCL1 (SPARC like 1)
Diseases named in the same sentence as SPARCL1 in open-access papers (continued):
Sharing a sentence is not in itself a finding about the gene and the disease.
corneal disease (1 paper, 2024). "In summary, we describe a novel autosomal dominant corneal stromal dystrophy associated with a missense variant in SPARCL1, extending the phenotypic and genetic heterogeneity of inherited corneal disease." (PMID 39169229, 2024).
depression (1 paper, 2020). "Sparcl1 levels are downregulated in the NAc of patients with depression, though its role in addiction is still unknown." (PMID 32694984, 2020).
heart failure (1 paper, 2025). Inability of the heart to pump blood at an adequate rate to meet tissue metabolic requirements. "In contrast, heart failure scores were higher in C2 Clu + Fibroblasts, while C1 Postn + Fibroblasts showed relatively lower scores, even below those of C0 Sparcl1 + Fibroblasts, which were predominantly derived from the Sham group." (PMID 40595870, 2025).
hilar cholangiocarcinoma (1 paper, 2018). A cholangiocarcinoma that arises from the junction, or adjacent to the junction, of the right and left hepatic ducts. "As reported, Loss of SPARCL1 was more observed in N1/2-stage and high/moderate-differentiated tumors than in N0-stage and poor/un-differentiated hilar cholangiocarcinoma, respectively." (PMID 29973149, 2018).
Impaired glucose tolerance (1 paper, 2022). An abnormal resistance to glucose, i.e., a reduction in the ability to maintain glucose levels in the blood stream within normal limits following oral or intravenous administration of glucose. "In addition, SPARCL1 treatment also promoted AT inflammation and impaired glucose tolerance, suggesting that SPARCL1 could be a mediator for the cross-talk between white AT and the liver in metabolic disorders." (PMID 35909571, 2022).
Insulin resistance (1 paper, 2025). Increased resistance towards insulin, that is, diminished effectiveness of insulin in reducing blood glucose levels. "SPARCL1 treatment also stimulates adipose tissue inflammation, which may exacerbate systemic insulin resistance." (PMID 40243151, 2025).
leukemia (1 paper, 2007). A malignant (clonal) hematologic disorder, involving hematopoietic stem cells and characterized by the presence of primitive or atypical myeloid or lymphoid cells in the bone marrow and the blood. "Thus far, differential expression of DOCK4 and SPARCL1 had never been associated to CD133+/CD34+ cell expansion or leukemias." (PMID 17559657, 2007).
lymph node metastasis (1 paper, 2022). "SPARCL1 expression was related to distant metastasis and lymph node metastasis in two studies, duke stage in two studies, and differentiation in two studies." (PMID 35111844, 2022). "The data of the correlation between SPARCL1 expression and distant metastasis, lymph node metastasis, or tumor differentiation and tumor stage were obtained from the four clinical studies." (PMID 35111844, 2022). "However, SPARCL1 expression was not related to lymph node metastasis (OR = 0.73, 95% CI: 0.39-1.37, p = 0.329)." (PMID 35111844, 2022).
Lymphatic Metastasis (1 paper, 2024). Transfer of a neoplasm from its primary site to lymph nodes or to distant parts of the body by way of the lymphatic system. "Patients with lymphatic metastasis exhibited upregulated SPARCL1 expression compared to those without metastasis." (PMID 39548034, 2024).
metastasis (1 paper, 2022). The spread or migration of cancer cells from one part of the body (where they first appeared) to another. "Our analysis was limited to four genes, ASPN, POSTN, SPARCL1, and MCAM, which we determined as potential markers of stromal activation in a xenograft model of PC bone metastasis." (PMID 36185585, 2022).
metastatic cancer (1 paper, 2021). A carcinoma which has spread from the original site of growth to another anatomic site. "We also observed CDH2, CP, HP, TF, and SERPINA5 were upregulated in liver metastatic cancer tissues and downregulated in primary cancer tissues; whereas SPARCL1 exhibited the opposite expression pattern." (PMID 34422629, 2021). "Therefore, in the observed tissues, SPARCL1 was most highly expressed in normal colorectal tissues, and CDH2 had the highest expression in normal liver tissues and liver metastatic cancer tissues, while CP, HP, TF, and SERPINA5 with the most highly expressed in normal liver tissues." (PMID 34422629, 2021).
oesophageal cancer (1 paper, 2024). "In oesophageal cancer, SPARCL1 was verified to inhibit cell proliferation, invasion, and glycolysis." (PMID 39548034, 2024).
osteoarthritis (1 paper, 2018). A noninflammatory degenerative joint disease occurring chiefly in older persons, characterized by degeneration of the articular cartilage, hypertrophy of bone at the margins and changes in the synovial membrane. "However, SPARCL1 is down-regulated during cartilage degeneration and associated with osteoarthritis." (PMID 29899321, 2018).
osteoporosis (1 paper, 2025). A condition of reduced bone mass, with decreased cortical thickness and a decrease in the number and size of the trabeculae of cancellous bone (but normal chemical composition), resulting in increased fracture incidence. "Subcluster analysis disclosed overall highest 31.86% CXCL10-PCC parathyroid chief cells, but SPARCL1-OC parathyroid oxyphil cells were higher in osteoporosis patients." (PMID 40496565, 2025). "In patients suffering with osteoporosis, SPARCL1-OC followed by HSP1IA-OC parathyroid oxyphil cells were highly clustered, while in non-osteoporosis patients CXCL10-PCC followed by S100A13-PCC parathyroid chief cells were highly clustered." (PMID 40496565, 2025).
ovarian tumor (1 paper, 2013). "The iTRAQ analysis also identified SPARC-like protein 1 (SPARCL1), described as having the capacity to suppress tumors, since expression is higher in the benign samples (FC = 2.82), and serum amyloid P-component (FC = 2.12), recently found by iTRAQ in ovarian tumor serum and tissue biopsies." (PMID 23557354, 2013).
renal carcinoma (1 paper, 2021). A carcinoma arising from the epithelium of the renal parenchyma or the renal pelvis. "However, some studies have shown that SPARCL1 inhibits cancer cell proliferation; SPARCL1 overexpression inhibits renal cancer cell migration and invasion, which is different from our study, where overexpression of the SPARCL1 gene did not affect sheep adipocyte proliferation." (PMID 34872433, 2021).
Sepsis (1 paper, 2025). Sepsis is defined as life-threatening organ dysfunction caused by a dysregulated host response to infection. "In sepsis, Microglia 1 exhibited strong upregulation of pro-inflammatory genes (e.g., GPNMB, CXCR4, HLA-DRB5) and downregulation of BBB-supportive genes (e.g., SPARCL1, MAP1B), indicating a highly reactive phenotype." (PMID 41030458, 2025).
status epilepticus (1 paper, 2020). Status epilepticus is defined as a continuous seizure lasting more than 30 min, or two or more seizures without full recovery of consciousness between any of them. "However, among the SPARC family proteins, the level of SPARCL-1 was increased and localized to excitatory synapses following status epilepticus (SE) in the rat lithium-pilocarpine seizure model." (PMID 33584170, 2020).
Trichiasis (1 paper, 2020). Inversion and rubbing of the eyelashes against the globe of the eye. "Histological analysis of conjunctival tissue from trichiasis patients has revealed inflammatory cell infiltrates and disrupted collagen structure consistent with the SPARCL1 knockout corneal injury model." (PMID 31964744, 2020).
urothelial carcinoma (1 paper, 2019). A malignant neoplasm derived from the transitional epithelium of the urinary tract (urinary bladder, ureter, urethra, or renal pelvis). "Methylation validation in urothelial carcinoma cell lines revealed that SPARCL1 methylation levels for all 4 of the CpG sites were significantly higher in J82, BFTC909, and T24 cell lines than in RT4 cell line." (PMID 30987093, 2019). "However, to the best of our knowledge, no report on the prognostic role of SPARCL1 in urothelial carcinoma has been published to date." (PMID 30987093, 2019). "Multivariate Cox regression analysis from 78 patients with solitary renal pelvic or ureteral pT3N0M0 urothelial carcinomas revealed that only negative SPARCL1 expression and nonpapillary tumour architecture were independently associated with systemic recurrence (p = 0.011 and 0.008, respectively)." (PMID 30987093, 2019).
viral infection (1 paper, 2025). "Expression of CXADR, BNIP3, or SPARCL1 was not downregulated by the ETV6/RUNX1 fusion in the absence of a viral infection (data not shown)." (PMID 41497616, 2025).
viral pneumonia (1 paper, 2024). Inflammation of the lung parenchyma that is caused by a viral infection. "To explore the role of endothelial SPARCL1 in the pathogenesis of viral pneumonia, we crossed VECadCreERT2 mice with novel Sparcl1flox mice." (PMID 38762489, 2024). "Whether SPARCL1 is involved in lung inflammation or contributes to viral pneumonia progression is unknown." (PMID 38762489, 2024).
tumor (63 papers, 2006 to 2026). "SPARCL1, known as a tumor suppressor, is associated with poorer survival in several cancers when downregulated." (PMID 38350915, 2024). "Elevated SPARCL1 expression was linked with advanced tumour stage, increased likelihood of lymphatic metastasis, and poorer prognosis in our clinical cohort." (PMID 39548034, 2024). "Sparcl1 (SPARC-like 1) is a type I secretory protein (650 amino acids) with three potential N-glycosylation sites and has been implicated as a tumor suppressor protein." (PMID 38474544, 2024). "In summary, comprehensive screening of DEGs and hub genes revealed that SPARCL1, a tumor suppressor in BC, has the potential to become a diagnostic biomarker and therapeutic target of BC and liver metastasis." (PMID 37180578, 2023). "Regarding our results, we found that the SPARCL1 expression was associated with distant metastasis, tumor differentiation, tumor stage, and overall survival, which shared similar results with the previous study." (PMID 35111844, 2022). "Previous results revealed a significant association between SPARCL1 and tumor-infiltrating lymphocytes in most cancers, we sought to verify the correlation between SPARCL1 and immune marker sets from the TIMER database." (PMID 36483097, 2022). "There was also an association between SPARCL1 expression and grade of tumor differentiation in which there was a significant declining levels of expression toward the poorly differentiated tumors." (PMID 32467737, 2020). "Secreted protein acidic and rich in cysteine like protein 1 (SPARCL1) is a matrix protein whose level is associated with tumor metastasis and prognosis." (PMID 28068412, 2017). "Pooled results from published clinical studies showed SPARCL1 expression was associated with differentiation (OR = 1.89, 95% CI: 1.38-2.59), tumor stage (OR = 0.47, 95% CI: 0.29-0.77), distant metastasis (OR = 0.53, 95% CI: 0.33-0.84), and overall survival (HR = 0.56, 95% CI: 0.43-0.74)." (PMID 35111844, 2022). "Furthermore, we investigated the correlations between SPARCL1 and immunological features, such as tumour mutation burden (TMB), immune activation processes, immune checkpoint expression, tumour immune dysfunction and exclusion (TIDE) scores, and chemotherapeutic sensitivity in BCa." (PMID 39548034, 2024). "Microarray and RNA sequencing datasets from GlioVis and TCGA, respectively, were used to assess SPARCL1 expression across whole-tumor samples." (PMID 42123596, 2026). "Spatially resolved gene expression data from Ivy GAP were used to assess SPARCL1 expression from defined tumor regions." (PMID 42123596, 2026). "Overexpression of SPARCL1 can inhibit the subcutaneous growth of tumor cells and their metastasis to the lungs, liver, and kidneys of mice, and recombinant SPARCL1 protein can also inhibit the growth of subcutaneous tumors." (PMID 42160309, 2026). "Transcriptomic analysis revealed that ADX downregulated tumor-induced transcripts in bone by over 90%, including osteogenic (Lox, Sparcl1, Bmp2, Postn, and Col1a1) and pro-angiogenic (Bmper, Pecam-1, and Esam) signatures." (PMID 42149634, 2026). "Spatial transcriptomics from Ivy GAP show SPARCL1 expression was upregulated along the leading edge and in infiltrating tumor regions." (PMID 42123596, 2026). "Specifically, ECM-associated genes such as SERPINH1, SPARCL1, and HYAL1 have been implicated in modulating immune cell behavior within the tumor milieu." (PMID 40426943, 2025). "In contrast, HNF4A, RASSF1, SPARCL1, and LHPP are associated with favourable outcomes: HNF4A regulates hepatocyte differentiation, RASSF1 acts as a tumour suppressor, SPARCL1 inhibits angiogenesis and metastasis, and LHPP suppresses tumour growth." (PMID 41007296, 2025). "Three of the top upregulated and most highly expressed DEGs in the majority of Ascl1-OE tumor cells are Tmsb4x, Sparcl1, and Mt3." (PMID 39609428, 2024).
tumor (continued). "The in vitro inhibition of BC cell proliferation, migration, and invasion by SPARCL1 indicates the gene acts as a tumor suppressor in BC." (PMID 37180578, 2023). "We identified SPARCL1 as a tumor suppressor in BC, which shows potential as a target for BC and liver metastasis therapy and diagnosis." (PMID 37180578, 2023). "SPARCL1, which was also down-regulated by hsa-mir-182, was proved to be able to optimize clinical efficacy by preventing tumor invasion and angiogenesis." (PMID 36138770, 2022). "By comparing the SPARCL1 transcriptional level in tumor and normal tissues, we demonstrated that SPARCL1 was generally aberrantly expressed in most tumor tissues compared with matched normal tissues." (PMID 36483097, 2022). "We evaluated the correlation between SPARCL1 transcriptional level and tumor-infiltrating lymphocytes across cancers." (PMID 36483097, 2022). "The expression of SPARCL1 in different tumor tissues and adjacent normal tissues was retrieved from the TIMER2.0 database." (PMID 36483097, 2022). "Secreted protein acidic and rich in cysteine-like 1 (SPARCL1) plays an important role in tumor pathogenesis." (PMID 35111844, 2022). "SPARCL1, a matricellular protein, can increase the neo-angiogenetic and infiltrative features of tumor and regulate the TME-dependent heterogeneity of endothelial cells." (PMID 35017463, 2022). "SPARCL1 expression was elevated in PDAC samples compared to the normal tissue and PC cell lines, and its expression was found to be downregulated in the late stages of PC indicating the role of SPARCL1 as a tumor suppressor gene." (PMID 36498893, 2022). "Considering the importance of tumor environment during cancer pathogenesis, the roles of SPARCL1 in tumor environment were comprehensively evaluated." (PMID 35111844, 2022). "Sparcl1 was previously considered to participate in a variety of physiological functions and closely related to tumor biology." (PMID 36387870, 2022). "SPARCL1 has been reported to be expressed in confluent endothelial cells and is one of the signature genes for tumor angiogenesis." (PMID 36397165, 2022). "In colorectal cancer, TME-dependent heterogeneity of tumor endothelial cells regulated by SPARCL1 has promoted tumor cell dormancy and vessel homeostasis." (PMID 35440049, 2022). "SPARCL1 is considered to be a potential tumor suppressor gene and participates in tumor development, by regulating tumor cell growth and proliferation." (PMID 35111844, 2022). "Although most studies verified that SPARCL1 was a potential tumor suppressor gene across cancer types, the results were not completely consistent, indicating different biological mechanisms of SPARCL1 in different cancers." (PMID 36483097, 2022). "We supposed that SPARCL1 played different roles that can promote tumorigenesis and inhibit tumor growth in different ECM environment." (PMID 36483097, 2022). "Meanwhile, we assessed the correlations between SPARCL1 and tumor-infiltrating lymphocytes across cancers." (PMID 36483097, 2022). "Unfortunately, the role of SPARCL1 in the pan-cancer cohort remained unclear, and few pan-cancer studies exist to illustrate the relationship between SPARCL1 and multiple tumor types." (PMID 36483097, 2022). "SPARCL1 significantly correlated with clinicopathological features and tumor microenvironment in CRC." (PMID 35111844, 2022). "Studies have shown that SPARCL1 inhibits tumour cell growth and serves as a marker for cancer detection and a therapeutic target." (PMID 34872433, 2021). "In summary, five candidate genes (TIMP1, SPARCL1, MYL9, TPM2, and CNN1) were finally characterized as the hub gene associated with tumor recurrence in CRC." (PMID 33897765, 2021). "SPARCL1 inhibited the progression of tumor cells from the G1 phase to the S phase and participated in the negative regulation of cell proliferation." (PMID 33980221, 2021).